FAP (fibroblast activation protein alpha)
Diseases named in the same sentence as FAP in open-access papers (continued):
Sharing a sentence is not in itself a finding about the gene and the disease.
cancer (continued). "Therefore, it still remains uncertain whether FAP+ fibroblasts are a conserved cell type across various cancer types." (PMID 40438108, 2025). "Moreover, recent studies revealed increased FAP expression in CAFs of PCa that correlate with PCa prognosis, and FAP targeting ligands are being evaluated as therapeutic carriers in multiple cancer patient trials." (PMID 38634185, 2025). "Based on previous studies, Fibro_FAP was classified as inflammatory cancer-associated fibroblast (iCAF)-like, Fibro_ACTA2 as myofibroblastic cancer-associated fibroblast (myCAF)-like, and Fibro_HLA-DRA and Fibro_AGR2 as antigen-presenting cancer-associated fibroblast (apCAF)-like." (PMID 39722065, 2025). "However, FAP targeting may be a useful way forward for the application of TRT to other cancer types." (PMID 41049848, 2025). "Additionally, ongoing research into the covalent binding of FAP with radiopharmaceuticals could further enhance the effectiveness of radionuclide therapy, potentially leading to significant advancements in cancer treatment." (PMID 41463267, 2025). "Furthermore, it must be mentioned that other molecular targets have also been successfully used for imaging pancreatic and other cancers, of which fibroblast activation protein (FAP) is probably the most popular today and is widely imaged with 68Ga labeled FAP inhibitors (68Ga-FAPI)." (PMID 39618940, 2024). "Finally, to clarify the molecular role of FAP in cancer progression, this study first integrated the information on FAP-binding and FAP co-expressed genes across all tumors for a series of enrichment analyses and identified the potential carcinogenic mechanism of FAP." (PMID 39055892, 2024). "The expression level of FAPα might also affect the proliferation of cancer cells themselves." (PMID 39596363, 2024). "Therefore, FAPα is an excellent target for cancer treatment." (PMID 39596363, 2024). "Notably, this included TGF-β (TGFB1, TGFB3), drivers of adenosine-mediated immune suppression (NT5E (CD73), ENTPD1 (CD39)), Wnt pathway ligands (WNT7A, WNT4), IL10 and drivers/markers of cancer-associated fibroblast activation (INHBA, WNT7A, TGFB1, FAP, PDGFRA, PDGFRB)." (PMID 39568014, 2024). "FAP is highly expressed on the cancer-associated fibroblasts’ membrane but not in normal tissue." (PMID 38611079, 2024). "Thus, consistent with in silico trajectories among FAP+ CAF clusters, these findings show that cancer cells promote a switch from a detoxification-associated inflammatory pathway (Detox-iCAF) to a myofibroblastic signature (ECM-myCAF) in FAP+ CAF both in vitro and in vivo." (PMID 38561380, 2024). "Furthermore, a small percentage of FNH and HCA demonstrated moderate to strong FAP expression, suggesting the FAP-expressing cancer-associated fibroblasts are not entirely specific to malignant lesions." (PMID 39664608, 2024). "Furthermore, as human tumors express higher levels of FAP than mouse tumors, anti-FAP NIR-PIT could demonstrate even more benefit in the human cancer clinical setting than in preclinical murine studies." (PMID 38275890, 2024). "Next to these compounds, other novel FAP tracers have also shown promising imaging results in preclinical and clinical case studies, and currently, multiple clinical trials for FAP-targeted theranostics are ongoing in various cancer types (e.g., NCT04849247, NCT05262855, NCT04939610, NCT04621435)." (PMID 39718718, 2024). "However, expression of FAP by malignant cells is limited to a few cancer types." (PMID 39086477, 2024). "Both wild-type and mutant FAPs caused comparable increases in cancer-related signaling pathways and the expression of matrix metalloproteinase 9 (MMP9), suggesting that FAP might exert intrinsic effects on cellular signaling independently of its enzymatic activity." (PMID 39765634, 2024).
cancer (continued). "Radiolabeled FAP inhibitors (FAPIs) have been recently developed as new promising radiotracers in an oncological setting, both as diagnostic imaging by Positron Emission Tomography/Computed Tomography (PET/CT) and as new anti-cancer treatment, in a theranostic perspective." (PMID 36765866, 2023). "Therefore, the present reports only suggest that FAP TRT may have efficacy in advanced cancer patients, and results of the first prospective studies are warranted." (PMID 36813980, 2023). "Therefore, FAP and FAP-expressing CAFs are attractive targets for cancer therapy." (PMID 36825204, 2023). "Therefore, FAP is a promising target for cancer diagnosis and therapy." (PMID 36986548, 2023). "Therefore, FAP is a new promising molecular target for the diagnosis of cancers." (PMID 36879039, 2023). "However, it is unclear whether high levels of CXCR4 and FAP represent distinct cancer states—especially in solid tumors." (PMID 36672341, 2023). "Thus, by analogy with FAPα-positive cancer cells, it may be assumed that FAPα-positive cells in fibrosis have a specific secretory phenotype, including the increased production of proinflammatory cytokines and angiogenesis regulators." (PMID 38136590, 2023). "However, there are reports of mesenchymal stem cells and cancer cells expressing FAP themselves." (PMID 38102692, 2023). "Fibroblast activation protein (FAP) is a membrane-tethered serine protease overexpressed in the reactive stromal fibroblasts of >90% human carcinomas, which makes it a promising target for developing radiopharmaceuticals for the imaging and therapy of carcinomas." (PMID 37375746, 2023). "In this study, we aimed to develop a series of albumin binder-truncated Evans blue (EB) modified FAP targeted radiotracers, and optimize the pharmacokinetic (PK) characteristics to overcome the existing limitations in order to apply in the radionuclide therapy of cancer." (PMID 34987657, 2022). "Moreover, it has been found that FAP+ stroma promotes cancer immune escape." (PMID 36263225, 2022). "Interestingly, FAP is not expressed in normal healthy tissue but overexpressed by cancer-associated fibroblasts of several tumor entities." (PMID 35904684, 2022). "Thus, radionuclide therapy targeting FAP may be highly effective for treating advanced cancer patients with widespread metastases." (PMID 35198057, 2022). "Nevertheless, high FAP expression is only associated with desmoplastic tumors, where [99mTc]Tc-iFAP SPECT/CT could be a useful guide for a theranostic approach to treating different types of cancer." (PMID 35631416, 2022). "However, FAP expression is detected in the stroma of more than 90% of human cancer." (PMID 35904684, 2022). "Therefore, FAP expression in cancer cells may be a useful predictive biomarker for patient outcomes." (PMID 35818720, 2022). "In PAAD, FAP+ CAF-abundant areas have been shown to be characterized by limited CD8+ lymphocytes infiltration, thereby indicating the contribution to the spatial exclusion of intra-tumoral CD8+ T cells, along with Tregs and neutrophil accumulation and cancer-associated pathways modulation." (PMID 36263225, 2022). "We further studied whether FAP affected cancer response to immune therapy." (PMID 35359436, 2022). "Moreover, it has been shown that increase of cancer-associated fibroblast markers (PDGFR-β, FAP, CD45, CD31) in the invasive front of the cancer might contribute to the invasive behavior of CRC cells." (PMID 33581319, 2021). "Similar to a previous study using 68Ga-FAPI-46 as an imaging agent for cancer patients, local uptake in the uterus of female subjects increased slowly within 1 h postinjection, which might be because of the higher physiological expression of FAP in the uterus." (PMID 33777814, 2021). "Hence, FAP is a promising specific theranostic target for cancer." (PMID 33777814, 2021).
cancer (continued). "Furthermore, the abundance of fibroblast activation protein (FAP), found to be more abundant in tissues with high MD, predicts a poor clinical response in various cancers, and is proving a viable target for inhibition to limit cancer progression." (PMID 34449016, 2021). "However, FAP expression in malignant cells is limited to a few cancer types." (PMID 34490078, 2021). "Thus, activated FAP is almost exclusively found in wound healing and in pathological conditions such as scar formations, liver cirrhosis, inflammation and cancer." (PMID 34638433, 2021). "Besides, the levels of FAP mRNA are increasing with the development of cancer progression." (PMID 34035230, 2021). "Moreover, advances have been made using therapies depleting FAP cells to treat cancer disease, which could potentially affect the heart." (PMID 33667270, 2021). "Although FAP can be expressed by malignant cells and is thought to contribute to their invasive properties, it is viewed primarily as a robust marker of non-malignant stromal cells, such as cancer-associated fibroblasts (CAFs)." (PMID 34282761, 2021). "Indeed, many FAP-targeted drugs are now undergoing preclinical or clinical development for treatment of a variety of cancers 12, 13, including anti-FAP antibodies 14, 15, FAP-activated prodrugs 16-19, FAP-targeted radiotherapeutic agents 20-22, and FAP-directed cancer imaging agents 23-25." (PMID 32483418, 2020). "Thus, FAP expression may be specific to CAFs surrounding cancer cells that infiltrate mucosa, but this hypothesis would need to be substantiated with further studies of a series of adenomatous polyps with high grade intraepithelial dysplasia." (PMID 32428869, 2020). "Thus, combined immunotherapy treatment consisting of T cells that target cancer cells and an agent targeting FAP α-expressing cells for destruction could increase the success of eliminating solid tumors and metastatic cells." (PMID 26985769, 2016). "FAP α is a tumor-associated antigen which is a serine protease involved in extracellular matrix remodeling and highly expressed on reactive stromal fibroblasts in >90% of human epithelial carcinomas, but is not detectable in normal adult human tissues." (PMID 26985769, 2016). "Thus, FAP has been considered as an emerging therapeutic target in cancer." (PMID 25474039, 2015). "Notably, some reports have observed FAP overexpression in both cancer cells and adjacent stroma." (PMID 25775399, 2015). "Carcinoma-associated fibroblasts (CAFs) are critical components of carcinoma-associated stromal cells, which are characterized by the overexpression of α-smooth muscle actin (α-SMA), fibroblast activation protein (FAP), fibroblast surface protein (FSP), and vimentin." (PMID 25909286, 2015). "However, a contraindication to any potential cancer therapy that indiscriminately depletes FAP+ cells might be their presence in normal tissues." (PMID 24605102, 2014). "Major systematic differences between normal and cancer-associated fibroblasts were the decreased basal levels of growth factors in CAFs and the capability of nemotic CAFs to start to regain the α-SMA expression and the increased FAP expression in nemosis compared to their normal counterparts." (PMID 19721715, 2009). "In cancer tissues, 93% (+/−SEM 1.3%) of the EpCAM-/FAP+ fibroblasts were also IL1R+ and 96% (+/−SEM 0.8%) were also Ly6C+, suggesting a high feature of plasticity between myCAF and iCAF populations." (PMID 40523922, 2025). "In this study, the differentiation of NFs into CAFs via co‐culture with cancer cells was confirmed by quantifying the mRNA expression levels of α‐SMA, FAP, FSP‐1, CSPG4, CXCL12, and HGF using qRT‐PCR." (PMID 39801758, 2025). "FAP has been thought to be a potential broad biomarker for CAF and been proven to play an important role in cancer growth." (PMID 40741380, 2025).
cancer (continued). "Fibroblasts, or their presence in 3D cancer models, provide an opportunity to test cancer drugs that target the fibroblasts, such as PDGFR-β and FAP-α." (PMID 40710292, 2025). "High-stiffness HGSOC tumors exhibited upregulated expression of HE4, α-SMA, FAP, and collagen I. rHE4 stimulated fibroblast activation and enhanced matrix contractility, whereas HE4 knockdown in cancer cells abrogated these pro-fibrotic effects." (PMID 41502510, 2025). "Conditioned by CDCP1-high SW480 or HCT116 cells, CAFs displayed a protumor phenotype with upregulation of α-SMA, FAP, PDGFRβ, and S100A4, indicating that cancer-cell CDCP1 promotes fibroblast activation." (PMID 41301830, 2025). "Together, we define FAP+ mesenchymal subpopulations in PDAC and identify their shared and cancer-specific phenotypic characteristics with mesenchymal cell subpopulations of the healthy pancreas." (PMID 40215177, 2025). "CAFs educated by shSMYD3 or shCDCP1 cancer cells displayed a marked reduction in protein levels of α-SMA, FAP, PDGFRβ and S100A4 compared with shNC controls (densitometry, mean ± SEM; p < 0.001)." (PMID 41301830, 2025). "Non-invasive imaging of FAP via positron emission tomography (PET) has emerged as a promising method for the detection and monitoring of cancer." (PMID 40430477, 2025). "Compared with other types of cancer, PDAC α‐SMA and FAP exhibit more severe fibrosis, with higher expression levels of α‐SMA and FAP." (PMID 41036616, 2025). "As a type II transmembrane serine protease, FAP exhibits both collagenase and gelatinase activities, playing a pivotal role in ECM remodeling and facilitating cancer cell migration, invasion, and metastasis." (PMID 40244052, 2025). "To determine whether the increased activity of the cancer-associated stroma, as indicated by increased citrate release, correlates with FAP and CD31, known markers of stromal formation, we correlated the expression of FAP versus pmCiC in the stroma and CD31 versus pmCiC expression in the stroma." (PMID 39022761, 2024). "This factor promotes the recruitment and activation of FAPα+ stellate cells, triggering the secretion of CXCL5 and inducing epithelial-mesenchymal transition in cancer cells, facilitating their invasion and promoting vessel co-option." (PMID 38453816, 2024). "To validate the cell specific expression, we performed RNA in situ hybridization for Claudin-4 and FAP-α, which were, as expected, seen in the SW480 cancer cells and the 1BR.3.G fibroblasts, respectively." (PMID 39011470, 2024). "Through this activity, FAP-expressing CAFs can remodel the ECM by cleaving collagen and altering bioactive signaling peptides in cancer." (PMID 39765634, 2024). "We aimed to address this by comparing FAP tracer behavior in FAP-transduced HT1080-huFAP and HEK293-huFAP cells, and endogenous FAP-expressing U-87 MG cancer cells and PS-1 pancreatic stellate cells." (PMID 39718718, 2024). "Among these, FAP and COL1A2 were involved in extracellular matrix remodeling and were upregulated in various cancers." (PMID 39456726, 2024). "Depletion of FAPα-expressing cells by antibodies, FAP CAR-T cells and various FAP vaccines has been widely investigated in the treatment of cancer and fibrosis and has shown safety and tolerability in phase I trials." (PMID 38783357, 2024). "An illustrative example is the use of 68Ga and 177Lu labeled peptides targeting fibroblast activation protein (FAP) and positron emission tomography (PET) in the development of cancer theranostics." (PMID 39898278, 2024). "Rapidly translated to clinical use, [68Ga]Ga-FAP-2286 PET imaging was performed on 64 patients, primarily with cancers of the head and neck, liver, stomach, pancreas, ovaries, and esophagus, for cancer staging or relapse identification." (PMID 39765634, 2024).
cancer (continued). "Collectively, the spatial distribution of all FAP+ CAF clusters is compatible with their plasticity and crosstalk with cancer or immune cells, and uncovers FAP+ CAF-immuno-permissive and immunosuppressive ECT (see Model)." (PMID 38561380, 2024). "In this context, the development of FAP-targeted imaging agents has opened new frontiers in nuclear medicine, providing tools to visualize and quantify the TME influence in cancer." (PMID 39765634, 2024). "By altering the ECM, FAP can modify the TME, and its overexpression on cancer reduces the effectiveness of CAR-T cell therapy in solid tumors and is linked to a poor prognosis in a number of malignancies." (PMID 39281684, 2024). "The quinoline-based FAP targeted radiotracer, FAPI-02, -04, -46, has demonstrated encouraging results with a high uptake in >80 patients across a variety of cancers." (PMID 39065684, 2024). "This has in turn supported the development of FAP-targeted PET tracers, which have been used to image at least 28 different cancer types in humans, including CCA." (PMID 39664608, 2024). "FAP targeting has emerged as a pivotal strategy for exploring the TME and enhancing cancer diagnostics." (PMID 39765634, 2024). "In contrast, in the setting of cancer, a recent study has developed a bispecific FAP-CD40 antibody, to induce CD40 stimulation solely in the presence of a fibroblast activation protein (FAP), to induce antitumor immunity." (PMID 39321281, 2024). "In the present study, we evaluated the expression of pmCiC, fibroblast activation protein-α (FAP) and the angiogenesis marker cluster of differentiation 31 (CD31) in human cancer tissues of different origins." (PMID 39022761, 2024). "In vivo and in vitro studies demonstrate that carcinoma cells can obtain CAF marker, such as alpha smooth muscle actin (α‐SMA), fibroblast activation protein (FAP) and vimentin." (PMID 38158643, 2024). "Furthermore, according to preclinical investigations, CAR T-cell therapy targeting FAP could be combined with cancer vaccines or immune checkpoint blockers such as anti-PD-1 and anti-CTLA4 and results in the blockade of some of the immunosuppressive factors such as DGKξ and TGF-β." (PMID 37316886, 2023). "Some of these studies also utilized cancer vaccines (e.g., HPV-E7) and immune checkpoint inhibitors (e.g., anti-CTLA 4) to increase inhibition of the immunosuppressive effects of FAP." (PMID 36853475, 2023). "This relationship between FAP and STAT3 (each is a therapeutic target in cancer) can be taken into account when creating more effective treatments in oncology." (PMID 36825204, 2023). "This study revealed that increased t-HHLA2 expression is related to lower NLR, and increased s-FAP expression is related to higher CRP levels, which is also a cancer biomarker." (PMID 36598731, 2023). "Indeed, CAF depletion may be enough to exert an indirect therapeutic effect given that FAP is upregulated on CAFs across a broad range of solid malignancies, appealing the idea that Nb-TriTE simultaneously targets cancer cells and immunosuppressive CAFs for T cell killing." (PMID 38031188, 2023). "Immunohistochemical FAP and glucose transporter 1 (GLUT1) expression of stromal and cancer cells was analyzed." (PMID 37024301, 2023). "FAP remodels the extracellular matrix (ECM) through its own enzymatic activity, thereby affecting the invasiveness and many other properties of cancer cells." (PMID 37509656, 2023). "By using chelators to connect FAP inhibitors (FAPI) or FAP antibodies to radionuclides and then performing PET/CT imaging, PET/MR imaging or SPECT imaging, the imaging research of malignant tumors targeting FAP was carried out." (PMID 36675506, 2023). "Here we examined the correlation between FAP expression and MSI in human cancers, and found that FAP was significantly and positively correlated with COAD and SARC." (PMID 37166418, 2023).